TNF (tumor necrosis factor)
Diseases named in the same sentence as TNF in open-access papers (continued):
Sharing a sentence is not in itself a finding about the gene and the disease.
lung carcinoma (continued). "This study aims to perform a comprehensive meta-analysis to resolve the ongoing debate regarding the relationship between these TNF-α polymorphisms and lung cancer risk." (PMID 39243014, 2024). "Ultimately, 29 case-control studies involving 6,265 lung cancer cases and 7,663 healthy subjects were analyzed to evaluate the association between TNF-α polymorphisms and lung cancer susceptibility." (PMID 39243014, 2024). "The investigation into TNF-α polymorphisms and lung cancer susceptibility reveals variability influenced by geographical, methodological, and demographic factors." (PMID 39243014, 2024). "Lowering pro-inflammatory cytokines, such as IL-1β, IL-2, IL-6, IL-8, IL-10, IL-12, interferon γ (IFN-γ), TNF-α, and granulocyte-macrophage colony-stimulating factor (CSF), can reduce lung cancer risk, particularly among smokers." (PMID 36986550, 2023). "TNF-α promotes pleural effusion of lung cancers by causing excessive permeability of airway blood vessels." (PMID 36986550, 2023). "Other published studies have suggested TGF-β1, interleukin IL-6, and TNF-α as possible diagnostic biomarkers for lung cancer due to their higher serum concentrations in patients with lung cancer." (PMID 37958349, 2023). "Lung cancer is also caused by chronic inflammation, and many pro-inflammatory genes, including TNF-α and IL-6, are crucial for apoptosis, proliferation, angiogenesis, and metastasis inhibition." (PMID 37894468, 2023). "The ROC plot analysis revealed that IL-1b, IL-2, IL-6, IL-10, IL-12p70, and TNF-alpha had a significant association with lung cancer, although with relatively low discriminative performance." (PMID 37373957, 2023). "High expression of certain cytokines (including IL-6, IL-8, and TNF-α) was linked to cancer cachexia, as exemplified by that IL-6 enclosed in lung cancer-derived extracellular vesicles would evoke muscle wasting by activating STAT3 pathway." (PMID 36581870, 2022). "Our data support the role of hepcidin, IL-6, and TNF-α in cancer-related anaemia and provide diagnostic values for predicting post-operative anaemia in lung cancer patients." (PMID 36612220, 2022). "In human lung cancer, tumor-associated macrophages secrete TNF-α, IL-10, and IFN-γ, which induce B7-H4 expression in lung cancer cells." (PMID 35410218, 2022). "In a preclinical study, lung cancer–induced osteoclastogenesis in vitro was associated with the upregulation of IL-6 and TNF-α and consequent activation of the AMPK/mTOR signaling pathway." (PMID 34950252, 2021). "As a result, differences in the mutational status of lung cancer subtypes were expected to cause changes in the levels of cytokines IL-6 and TNF-α." (PMID 34439874, 2021). "Other studies showed that the rs1800629 G > A polymorphism in the TNF gene is associated with an increased risk of lung cancer, especially among Asians and Tunisians." (PMID 33917839, 2021). "TNF produced by malignant cells can also cause excessive permeability of existing blood vessels, thus stimulating pleural effusion in lung cancer models." (PMID 34079469, 2021). "This is illustrated by the finding that specific genetic polymorphisms of the TNF gene region impact lung cancer progression differently." (PMID 34445397, 2021). "More recently, preliminary results from a safety clinical trial (NCT02092467) revealed an increased risk of malignancies, especially lung cancer, upon Tofacitinib treatment compared to treatment with tumor necrosis factor (TNF) inhibitors." (PMID 34073410, 2021). "Encoded by TNF, TNF-α was associated with apoptosis in the natural killer cell-based therapeutics on lung cancer." (PMID 32595734, 2020). "There were suggestive associations of TNF with venous thromboembolism (OR 2.18; 95% CI 1.32, 3.59), endometrial cancer (OR 0.25; 95% CI 0.07, 0.94), and lung cancer (OR 0.45; 95% CI 0.21, 0.94)." (PMID 32805626, 2020).
lung carcinoma (continued). "Bioinformatics analysis of lung cancer patients revealed that higher expression of TNF-α was associated with a low risk of cancer progression." (PMID 32527042, 2020). "Chronic increase of TNF has been historically related to cancer-associated cachexia due to its effects on hypothalamic structures, and high serum TNF levels have been associated with worse prognosis in lung cancer." (PMID 32039025, 2019). "Meanwhile, GSC suppressed TNFα inducing NF-κB activation and increased the susceptibility of lung cancer cell to TNFα induced apoptosis." (PMID 29379440, 2017). "In summary, the present study shows that rSFV can efficiently infect lung carcinoma cells in vitro and exploit them for production of functional rSFV-encoded TNF-α and IFN-γ." (PMID 29276511, 2017). "Studies have found that down-regulation of claudin-1 expression is induced by TNF-α is regulated by the PKCδ–iPLA2–PGE2–PPARγ signaling cascade in human lung carcinoma A549 cells, which caused the change of morphology and migration ability." (PMID 29311822, 2017). "In patients with lung cancer, polymorphisms in TNF and IL6 were significantly associated with pain severity (for TNF, GG = 4.12; GA = 5.38; AA = 5.50; p = 0.04) and with morphine-equivalent daily dose (IL-6, GG = 69.61; GC = 93.6; CC = 181.67; p = 0.004)." (PMID 26269716, 2015). "In this study, we conducted a meta-analysis on high-throughput gene expression data to identify TNF-α-mediated genes implicated in lung cancer." (PMID 25548907, 2014). "This variant located within the promoter region of the gene has been associated with increased and decreased TNFα production, as well as increased risk of radiation-induced toxicity after treatment for lung cancer." (PMID 23991131, 2013). "However, a comprehensive patient evaluation should include disease duration, time from anti-TNFα implementation, and additional risk factors for lung cancer (e.g., smoking or COPD)." (PMID 40282506, 2025). "This meta-analysis of ten case-control studies, with 2,427 cancer cases and 2,357 controls, uncovers a complex relationship between the TNF-α -238G > A polymorphism and lung cancer risk, showing both risk and protective effects that vary by genotype and population." (PMID 39243014, 2024). "However, several limitations are noted, including small sample sizes in studies on the TNF-α -238G > A polymorphism, which diminish statistical power and the ability to establish a clear correlation with lung cancer risk." (PMID 39243014, 2024). "Our analysis of 19 case-control studies involving 3,838 cases and 5,306 controls indicates that the TNF-α -308G > A polymorphism may affect lung cancer risk in a population-specific manner." (PMID 39243014, 2024). "Further, the combined IL-4 and TNF-α treatment had been found to cause synergistic augmentation in PD-L1-expression in renal carcinoma cells while the inductive effect of IL-1β on PD-L1-expression had been demonstrated in lung cancer and glioma cell lines." (PMID 39445017, 2024). "Moreover, the ROC plot analysis revealed that several inflammatory markers, including IL-1b, IL-2, IL-6, IL-10, IL-12p70, and TNF-alpha, are significantly associated with the risk of lung cancer." (PMID 37373957, 2023). "Previous studies have reported that tobacco smoking could induce the inflammation associated with the TNF and NFκB signaling pathways, promoting the development of lung cancer." (PMID 37475016, 2023). "This indicates that excessive immunosuppression could lead to the progression of lung cancer as anti-TNF treatment has been reported to increase the risk of cancer." (PMID 37638979, 2023). "Lastly, the study investigated the potential of TNF-α as a diagnostic marker for lung cancer." (PMID 37373987, 2023).
lung carcinoma (continued). "Notably, elevated serum levels of IL-1β, IL-10, and TNF-α were linked to lung cancer risk only in the African American population." (PMID 38067398, 2023). "Notably, elevated levels of IL-1β, IL-10, and TNF-α were linked to lung cancer risk only in the African American population." (PMID 38067398, 2023). "Statistical significance was observed for IL-1b (p = 0.044), IL-2 (p = 0.040), IL-6 (p = 0.001), IL-10 (p = 0.008), IL-12p70 (p = 0.001), and TNF-alpha (p = 0.046), indicating that these inflammatory markers are significantly associated with the risk of lung cancer." (PMID 37373957, 2023). "Moreover, a previous study also reported that the level of IL-1β, IL-6, and TNF-α was notably up-regulated in lung cancer with Qi-yin deficiency." (PMID 35292015, 2022). "The decreased levels of inflammatory factors (IL-6, IL-8, and TNF-α) strongly associated with curcumin administration (180 mg/day; ~cmax 0.5 μmol/l in human plasma) in patients with cancer, including those with lung cancer, imply a possible reduction of the M2 TAM phenotype." (PMID 34834295, 2021). "The downregulation of TNFR1 is associated with decreased effectiveness of TNF-α, pointing to a potential mechanism lung cancer cells may use to evade TNF-α." (PMID 33262947, 2020). "This MR study found evidence of causal associations of increased TNF levels with higher risk of coronary artery disease, ischaemic stroke, and venous thromboembolism and decreased risk of overall, colorectal, breast, endometrial, and lung cancer." (PMID 32805626, 2020). "Furthermore, we revealed inverse associations of TNF levels with risk of overall cancer and several site-specific cancers (colorectal, breast, endometrial, and lung cancers)." (PMID 32805626, 2020). "We have previously reported that TGF-β-induced epithelial-to-mesenchymal transition (EMT) of A549 lung cancer cells can be augmented by tumor necrosis factor-α (TNF-α), resulting in loss of their adhesive properties and gain of migratory and invasive abilities characteristic to mesenchymal cells." (PMID 32357159, 2020). "The decreased levels of interleukin-6 and tumor necrosis factor-α may be associated with lower risk of lung cancer." (PMID 30723700, 2019). "In conclusion, our findings demonstrate that ATM, which could be activated by lung cancer-associated TNF-α, up-regulate MMP-13 expression and thereby augment tumor metastasis." (PMID 27556690, 2016). "As lung carcinoma epithelium cell with K-ras mutation have higher level of TNF-α, the higher level of pro-inflammatory cytokines might be due to the overall effects of oncogene activation." (PMID 27556690, 2016). "Thus, SIRT1 is involved in B[a]P-induced transformation associated with activation of the TNF-α/β-catenin axis and is as a potential therapeutic target for lung cancer." (PMID 26318035, 2015). "The pretreatment with BTC could increase the resistance of lung cancer cells against TNF-α/CHX-induced apoptosis in a dose-associated pattern." (PMID 24629040, 2014). "In addition, elevated levels of TNF-α or IFN-γ is linked with the development of lung cancer." (PMID 38813211, 2024). "The fact that curcumin administration in patients with cancer, including lung cancer, is strongly associated with a decreased level of inflammatory factors (interleukin 6 (IL-6), interleukin 8 (IL-8), and tumour necrosis factor alpha (TNF-α)) implies its strong potential for metastasis suppression." (PMID 34834295, 2021). "Moreover, we identified key FDY2004-targeted oncogenic and tumor-suppressive pathways associated with lung cancer, including the phosphatidylinositol 3-kinase-Akt, mitogen-activated protein kinase, tumor necrosis factor, Ras, focal adhesion, and hypoxia-inducible factor-1 signaling pathways." (PMID 33628308, 2021).
lung carcinoma (continued). "Genetically predicted TNF levels showed a suggestive positive association with risk of venous thromboembolism (OR 2.18, 95% CI 1.32, 3.59) and inverse associations with risk of endometrial cancer (OR 0.25, 95% CI 0.07, 0.94) and lung cancer (OR 0.45, 95% CI 0.21, 0.94)." (PMID 32805626, 2020). "Comparison and efficacy evaluation of IL-6 and TNF-a levels before and after chemotherapy in the two groups of patients with lung cancer." (PMID 40265008, 2025). "circFUT8 plays an important regulatory role in lung cancer cells by modulating the expression of macrophage differentiation and TNF signaling pathway‐related genes." (PMID 41328768, 2025). "A similar pattern was observed in the general Korean population, with thyroid cancer being the most frequent malignancy in individuals aged <40 years and lung cancer in those aged ≥40 years, consistent with our AS cohort receiving TNF inhibitors." (PMID 41302997, 2025). "Lung cancer cells amplify this cascade autonomously via TNF-α and HMGB1 secretion, creating a self-reinforcing NF-κB activation loop." (PMID 40510156, 2025). "Lf activates macrophages and enhances TNF-α production, whereas it suppresses TNF-α production under conditions of chronic endometritis, pregnancy, and lung cancer." (PMID 40867618, 2025). "Lung cancer mirrored this, with high SP100 and SP140 expression linked to better prognosis, involving apoptotic (TNF-α, caspase) and TAM-mediated immune pathways, respectively." (PMID 41188771, 2025). "Clinically, elevated circulating TNF-α predicts poor prognosis in colorectal, breast, and lung cancers, while pilot studies in HF cohorts link higher TNF-α concentrations to cachexia, sarcopaenia, and adverse ventricular remodeling." (PMID 41473193, 2025). "For instance, lidocaine inhibited lung cancer cell migration induced by tumor necrosis factor alpha (TNF-α) by blocking Src (Src family of protein tyrosine kinases) signaling, a key pathway in inflammatory vascular hyperpermeability." (PMID 40941021, 2025). "In murine lung cancer models, tumor cell‐secreted TNF‐α activates NF‐κB signaling, potentiating their tumoricidal activity in lung cancer models." (PMID 41427020, 2025). "A comparable prevalence of lung cancer was described in RA patients treated with various anti-TNFα therapies." (PMID 40282506, 2025). "Ganoderma lucidum polysaccharides activate NK cells through Toll-like receptor (TLR) signaling, stimulating the release of cytokines such as IFN-γ and TNF-α, which are especially beneficial in liver and lung cancer treatments." (PMID 40406101, 2025). "The results suggest that rutin promotes the tumor necrosis factor-α (TNF-α)-induced apoptosis of A549 human lung carcinoma cells." (PMID 41142938, 2025). "This approach is now being used with nivolumab and anti-TNF-α therapy in resectable lung cancer patients (NCT04991025)." (PMID 39762215, 2025). "Findings from functional enrichment analysis indicated that the parental genes of annotated circRNAs were associated with TNF, Rap1, and MAPK signaling pathways, which have been linked to lung cancer development." (PMID 40780118, 2025). "Palbociclib induces Rb-mediated senescence and NF-κB-driven pro-inflammatory SASP in tumor cells, including TNF-α and IL-15, thereby leading to NK cell infiltration in lung cancer mouse model." (PMID 41463246, 2025). "This study confirmed that the TNF signaling pathway plays a crucial role in the apoptosis of lung cancer A549 cells through the co-regulation of NF-κB and MAPK pathways." (PMID 40552155, 2025). "We detected higher TNF mRNA levels in PBMCs from patients with lung cancer compared to healthy control subjects, suggesting enhanced inflammatory activity in the peripheral blood and indicating a systemic immune response associated with lung cancer." (PMID 40895524, 2025). "Neutralization of IFN-γ and TNF-α or depletion of CD8+ T cells slows the growth of lung cancer but accelerates the growth of other cancers." (PMID 40553564, 2025).
lung carcinoma (continued). "These are tightly interconnected pathways; TNF-α is known to induce ROS production in lung cancer cells, promoting oxidative DNA damage and contributing to tumor progression." (PMID 40770488, 2025). "By observing the changes of inflammatory cytokine levels after chemotherapy intervention, we found that the difference between IL-6 and TNF-α of the 85 patients with lung cancer was gradually reduced after chemotherapy." (PMID 40265008, 2025). "Parallel observations from Chinese lung cancer cohorts included enriched TNF-α pathway activity and higher plasma TNF levels, while elevated IL-10/CCL2 in elderly patients and ST6GAL1 in high-grade irAEs further highlight shared inflammatory axes." (PMID 40722787, 2025). "Lung cancer CAFs produce inflammatory mediators such as interleukin (IL)-6, IL-8, IL-17, IL-22, tumor necrosis factor (TNF)-α, and vascular endothelial growth factor (VEGF) to support progression, invasion, and angiogenesis." (PMID 39403603, 2024). "Overall, treatment with cisplatin increased the abundance of m6A modifiers, whereas TNF-α treatment decreased their expression in cervical, breast, and lung cancer cell lines." (PMID 38665783, 2024). "TRAF2 is a well-known regulator protein of TNFα-NFκB signaling, shown to be enriched in the GSEA analysis of lung cancer patients with KEAP1 mutation in sites R320 and R470." (PMID 38184997, 2024). "Rutin has been documented to enhance A549 human lung carcinoma cell apoptosis through the induction of the TNF-α signaling pathway." (PMID 38256842, 2024). "Further, TNF-a and GR are known to work cooperatively to activate pro-inflammatory pathways in human lung cancer cell line A549s, despite the usual anti-inflammatory function of GR." (PMID 38912926, 2024). "Those associated with lung cancer include interleukin-4 (IL-4), IL-6, monocyte chemotactic protein-1 (MCP-1), and tumor necrosis factor-alpha (TNF-α)." (PMID 39042180, 2024). "In this study, we found that pyroptosis-related cytokines IFN-γ, IP-10, MIP-1α, MIP-1β, MIP-2 and TNF-α are the potential markers for lung cancer diagnosis." (PMID 38813211, 2024). "IL-8, IFN-γ, and TNF-α displayed significantly elevated expression levels in both AA and WA lung cancer patients compared to their respective counterparts (all p < 0.05)." (PMID 38276239, 2024). "Leptin dose-dependently promotes naïve CD4+ T cell proliferation and polarizes CD4+ T cells towards a Th1 phenotype, which in turn facilitates lung cancer secretion of inflammatory cytokines such as TNF-α and IL-6, promoting lung cancer bone metastasis." (PMID 38571500, 2024). "When lung tissue cells transform into lung cancer cells, immune cells release these chemokines to facilitate infiltration into tumor tissue and release TNF-α and IFN-γ to eliminate the cancer cells." (PMID 38813211, 2024). "IL-8, IFN-γ, and TNF-α exhibited elevated levels in both AA and White American (WA) lung cancer cases." (PMID 38276239, 2024). "The levels of IL-8, IFN-γ, and TNF-α were elevated in both AA and White American (WA) lung cancer cases." (PMID 38276239, 2024). "Cytokines released during the apoptosis of lung cancer cells, such as TNF-α, TGF-β, and VEGF, can indirectly promote bone metastasis by fostering inflammation and angiogenesis within the tumor microenvironment." (PMID 38571500, 2024). "Last, β-catenin gene CTNNB1 and TNF expression levels were positively correlated in AMs of patients with lung cancer." (PMID 37092550, 2023). "Withanolides were also found to suppress TGF-b1 and TNF-a induced Epithelial-Mesenchymal Transition (EMT) in the lung cancer cell lines H129 and A549." (PMID 36865913, 2023). "Genes upregulated in cluster 2 are involved in interferon γ signaling, TNF α, and allograft rejection, suggesting an immunomodulatory role for iloprost, as has been shown in mouse models of pulmonary hypertension and lung carcinoma." (PMID 37711198, 2023).